PML (PML nuclear body scaffold)
Diseases named in the same sentence as PML in open-access papers (continued):
Sharing a sentence is not in itself a finding about the gene and the disease.
acute promyelocytic leukemia (continued). "Some forms of acute myelogenous leukemia (AML) share typical morphological and immunophenotypic features of acute promyelocytic leukemia (APL) but are negative for promyelocytic leukemia-retinoic acid receptor alpha (PML-RARA) fusion." (PMID 36465368, 2022). "They resemble classical acute promyelocytic leukemia (APL) patients in clinical features, morphology, and immunophenotype but do not carry the promyelocytic leukemia (PML)-RARA fusion gene." (PMID 36185228, 2022). "PML-RARα functions as a dominant negative form and causes acute promyelocytic leukemia (APL)." (PMID 35594310, 2022). "Promyelocytic leukemia has recently been identified as an antiviral host cellular determinant capable of restricting all serotypes of DENV, another Flaviviridae family member, as siRNA-mediated depletion of PML resulted in increased virus production." (PMID 34513832, 2021). "AML with RUNX1-RUNX1T1 or CBFB-MYH11 and acute promyelocytic leukemia with PML-RARA are considered to be acute leukemias without regard to blast cell count." (PMID 34135310, 2021). "In support of this, analysis of acute promyelocytic leukemia (APL) that developed after treatment with mitoxantrone occurred within a tight 8bp cluster ‘hotspot’ within the PML intron 6, a region that topoisomerase-II proteins could cleave upon treatment with etoposide or doxorubicin." (PMID 34200309, 2021). "Acute promyelocytic leukemia (APL) is characterized by the presence of a chromosomal translocation between the retinoic acid receptor-alpha (RARα) gene on chromosome 17 and the promyelocytic leukemia protein (PML) gene on chromosome 15, resulting in the PML-RARα fusion gene." (PMID 32168763, 2020). "Some acute myeloid leukemia (AML) patients present with features mimicking the classical hypergranular subtype of acute promyelocytic leukemia (APL) but without the typical promyelocytic leukemia/retinoic acid receptor α (PML/RARα) rearrangement." (PMID 33019444, 2020). "However, the most successful pharmacological treatment of AML is still all-trans retinoic acid (ATRA)-based differentiation therapy of acute promyelocytic leukemia (APL), a particular subtype of AML defined by the PML-RARA rearrangement." (PMID 33176741, 2020). "Moreover, PML is the main therapeutic target of arsenic trioxide (ATO), a drug approved for the treatment of acute promyelocytic leukemia and shown to have anti‐HIV‐1 latency potential in vitro and in vivo." (PMID 32157726, 2020). "Finally, a study performed on a subtype of AML, Acute Promyelocytic Leukemia (APML; AML-M3) expressing the oncogenic fusion protein PML-RARα, detected the PML-RARα transcript in TEVs." (PMID 31137912, 2019). "This is the case for Acute Promyelocytic Leukemias (APL) where SUMOylation, and subsequent destruction, of the PML-RARα fusion oncoprotein are triggered by arsenic trioxide, which is used as front-line therapy in combination with retinoic acid to cure APL patients." (PMID 31405039, 2019). "The notable exception being acute promyelocytic leukemia (APL) with the development of all-trans retinoic acid (ATRA) and arsenic trioxide (ATO) to overcome the block in myeloid differentiation due to the PML-RARα fusion protein created by the translocation 15;17." (PMID 28197208, 2017). "Acute Promyelocytic Leukemia (APL) is a subtype of Acute Myeloid Leukemia (AML) with the characteristic chromosomal translocation involving retinoic acid receptor alpha (RARA) gene and Promyelocytic leukemia protein (PML) gene." (PMID 27929140, 2016). "Acute promyelocytic leukemia (APL) is characterized by a balanced translocation between chromosome 17q21 and chromosome 15q22, leading to an abnormal fusion protein called promyelocytic leukemia-retinoic acid receptor alpha (PML-RARA)." (PMID 27322078, 2016).
acute promyelocytic leukemia (continued). "Arsenic trioxide (ATO), which is used to treat patients with acute promyelocytic leukemia (APL), binds to thiol groups in cysteine residues and induces degradation of proteins, such as promyelocytic leukemia protein (PML) and PML-retinoic acid receptor α (PML-RARα) fusion protein." (PMID 26732534, 2015). "Promyelocytic leukemia-RARα is, like PML, phosphorylated by ERK1/2 in response to As2O3 and, then, highly conjugated to SUMO2/3, since it retains two of the three major PML SUMOylation sites at K65 and K160." (PMID 23734343, 2013). "Acute promyelocytic leukemia (APL) is a distinct type of acute myeloid leukemia (AML) characterized by specific morphology (M3 in the FAB classification), frequent association of a coagulopathy, the t(15:17) translocation resulting in the fusion protein PML-RARα." (PMID 22084652, 2011). "The signature protein of PML NBs is the promyelocytic leukemia gene product because PML-negative cells are unable to form nuclear bodies and other PML NB components show a dispersed nuclear distribution." (PMID 20205709, 2010). "In addition, this protein represents one of the two fusion partners in the PML/retinoic acid receptor alpha (RARA) fusion oncoprotein, which supports tumorigenesis in patients with acute promyelocytic leukemia." (PMID 21092142, 2010). "Interestingly, despite a significant increase in intracellular ROS (reactive oxygen species), suggesting a contribution to cytotoxicity, no substantial change in the biogenesis of promyelocytic leukemia nuclear bodies (PML-NBs) was detected." (PMID 41154590, 2025). "Acute promyelocytic leukemia (APL) is a subtype of acute myeloid leukemia (AML), characterized by a fusion between the PML and RARA genes and by a block in the myeloid maturation at the promyelocytic stage." (PMID 41168841, 2025). "The chimeric gene PML-RARα, responsible for acute promyelocytic leukemia (APL), is targeted by ATO, an established therapy for APL." (PMID 41026253, 2025). "Examples in this respect are BCR::ABL and PML::RAR found in chronic myeloid leukemia (CML) and acute promyelocytic leukemia (APL) respectively." (PMID 40979168, 2025). "PML-RARA, characteristic of acute promyelocytic leukemia (APL), disrupts the retinoic acid receptor (RAR) pathway, blocking transcriptional activation required for differentiation." (PMID 41280924, 2025). "In acute promyelocytic leukemia (APL), TRIM19 fuses with the retinoic acid receptor alpha gene (RARA) to form the PML-RARA gene." (PMID 38225560, 2024). "Reprogramming of hematopoietic stem and progenitor cells by PML::RARA leads to aberrant self-renewal, a precursor to the development of APL (acute promyelocytic leukemia)." (PMID 38648485, 2024). "Acute promyelocytic leukemia (APL), one of the best studied forms of AML, is characterized in ~95% of cases by the chromosomal translocation t(15:17), responsible for the generation of the PML/RARα oncoprotein and the consequent block of blasts differentiation processes." (PMID 36536122, 2023). "In opposition to its pro-survival role, autophagy is also involved in the degradation of the fusion proteins PML-RARA and BCR-ABL which contribute to antileukemic responses in acute promyelocytic leukemia (APL) and chronic myeloid leukemia (CML), respectively." (PMID 37296673, 2023). "Acute promyelocytic leukemia (APL) is a subtype of AML characterized by chromosomal translocation t(15:17), which forms a chimeric PML-RARA protein complex that impedes myeloid precursor maturation." (PMID 38201290, 2023). "PRMT5 is also highly expressed in acute promyelocytic leukemia (APL), an AML subtype mainly driven by the PML-RARα oncoprotein." (PMID 36358861, 2022). "In acute promyelocytic leukemia (APL)-ascites mouse model and APL cell lines, lncRNA HOTAIRM1 facilitates formation of autophagosome to degrade oncoprotein PML nuclear body scaffold (PML)-retinoic acid receptor alpha (RARA) via targeting miR-20a." (PMID 34722769, 2021).
acute promyelocytic leukemia (continued). "Interestingly, this effect is seen with the oncogenic fusion protein PML-RARα (TRIM19), whose autophagic degradation is induced in following exposure to all-trans retinoic acid, which is a standard treatment for acute promyelocytic leukemia." (PMID 32226386, 2020). "In acute promyelocytic leukemia (APL), the direct molecular target of all-trans-retinoic acid (ATRA) in human myeloid cells is the PML-RARα oncoprotein that mediates differentiation." (PMID 32660524, 2020). "In acute promyelocytic leukemia (APL), the formation of chimeric proteins such as RUNX1-RUNX1T1 and PML-RARA alter the normal maturation process of myeloid precursor cells." (PMID 33291428, 2020). "As is known to all, acute promyelocytic leukemia (APL) is a particular subtype in AML, characterized by a balanced reciprocal translocation between chromosomes 15 and 17, which leads to the fusion between promyelocytic leukemia (PML) gene and retinoic acid receptor α (RARα)." (PMID 32400873, 2020). "For example, in acute promyelocytic leukemia (APL), PML/RARα appears to directly control the transcription of the immunoproteasome subunits, contributing to lowered expression of PSMB8-10 in APL cells." (PMID 32850906, 2020). "The interaction of S100A3 with RARα is observed in breast cancer and lung cancer, acute-myeloid-leukemia (AML) as well as acute promyelocytic leukemia (APL) cells, in which S100A3 binds also to PML-RARα." (PMID 30532072, 2019). "Acute promyelocytic leukemia (APL) is a subtype of AML characterized by a reciprocal and balanced translocation involving retinoic acid receptor α (RARa) on chromosome 17 and promyelocytic leukemia (PML) on chromosome 15 which generates the oncogenic PML-RARα fusion protein." (PMID 31905996, 2019). "In acute promyelocytic leukemia (APL), treatment with all-trans retinoic acid (ATRA) reverses promyelocytic leukemia-retinoic acid receptor α (PML-RARα)-mediated differentiation block at the promyelocyte stage resulting in mature neutrophil-like cells." (PMID 29593731, 2018). "For example, prevalent detection of BCR-ABL1 fusions in CML cases may be useful in prescribing tyrosine kinase inhibitor (TKI) treatment regimens such as imatinib, while detection of PML-RARa fusions may require treatments designed to treat the M3 AML subtype, acute promyelocytic leukemia (APL)." (PMID 28743306, 2017). "One classical example of a TFFG is the fusion between the promyelocytic leukemia (PML) gene and the transcription factor, retinoic acid receptor alpha (RARA), which is seen in 95% of acute promyelocytic leukemia (APL) patients." (PMID 29299133, 2017). "The 5th edition of the World Health Organization (WHO) Classification of Hematolymphoid Tumors recognizes acute promyelocytic leukemia (APL) as a subtype of acute myeloid leukemia (AML) defined by the presence of a genetic abnormality, namely the PML::RARA gene fusion." (PMID 40095699, 2025). "Although RARα was initially shown to be an oncogenic driver as a fusion product of promyelocytic leukemia (PML) and RARA genes in acute promyelocytic leukemia (APL) 9, recent reports have demonstrated that native RARα possesses oncogenic properties itself 10-14." (PMID 39744424, 2025). "Di Croce found that PML-RAR fusion protein, an oncogenic transcription factor, recruited DNMT1 and DNMT3A to retinoic acid receptor beta 2 leading to its methylation and subsequent gene silencing in acute promyelocytic leukemia (APL)." (PMID 38696033, 2024). "Rearrangements of the RARG gene, rather than of the RARA gene, have been identified in acute promyelocytic leukemia patients and involved the NUP98 (for nucleoporin, 3 patients), CPSF6 (encodes an RNA-binding protein, 4 patients), NPM1 (for nucleophosmin, 1 patient), and PML (1 patient) genes." (PMID 37569466, 2023).
acute promyelocytic leukemia (continued). "Acute promyelocytic leukemia (APL) is a type of AML characterized by an accumulation of immature granulocytes, promyelocytes, that harbor genetic translocations in the retinoic acid receptor alpha gene (RARα) that generates the PML/RARα gene, PRα." (PMID 36694243, 2023). "Acute promyelocytic leukemia (APL) is a distinct subclass of acute myeloid leukemia (AML) which is characterized by a reciprocal and balanced translocation between the promyelocytic leukemia protein (PML) gene on chromosome 15 and the retinoic acid receptor α (RARα) gene on chromosome 17." (PMID 35193533, 2022). "However, very few patients have typical morphological and immunophenotypic characteristics of APL (e.g., promyelocytes containing coarse azurophile granules and Auer bodies) but are negative for promyelocytic leukemia-retinoic acid receptor alpha (PML-RARA) fusion." (PMID 36465368, 2022). "In a separate study, expression of the oncogenic fusion proteins PML-RARA and AML1-ETO found in acute promyelocytic leukemia (APL) and some non-APL AMLs, respectively, was associated with the loss of the 2B4 ligand CD48 on the leukemia cell surface." (PMID 31681270, 2019). "However, unlike iAsIII, methylarsine oxide could not induce degradation of Promyelocytic leukemia-retinoic acid receptor alpha (PML-RARα) fusion protein in APL cells." (PMID 28108741, 2017). "Promyelocytic leukemia protein (PML) is a protein originally identified as part of a t(15:17) chromosomal translocation resulting in the fusion of PML and retinoic acid receptor alpha genes in acute promyelocytic leukemia (APL) patients (1, –, 5)." (PMID 28074026, 2017). "Acute promyelocytic leukemia (APL) is a distinct subtype of AML that is characterized by a specific chromosome translocation, which results in the fusion of the promyelocytic leukemia (PML) gene and the retinoic acid receptor α gene (RARα)." (PMID 25797266, 2015). "The fourth identified variant c.G1487T/p.G496V affects a non-conserved amino acid in a known Promyelocytic Leukemia tumor suppressor [PML] gene in Acute Promyelocytic Leukemia (APL)." (PMID 24907849, 2014). "Promyelocytic leukemia protein (PML) is a tumor suppressor protein, originally identified as a fusion partner of the retinoid acid receptor (RAR) gene characteristic of chromosomal translocation involved in acute promyelocytic leukemia (APL)." (PMID 22947142, 2012). "Moreover, RHOBTB2 expression was increased in non-acute promyelocytic leukemia (APL) subtypes, patients without FLT3 mutation and PML/RAR fusion, and imparted a positive correlation with the expression of FLT3, FHL1, and RUNXs." (PMID 34074803, 2021).
leukemia (260 papers, 2006 to 2026). A malignant (clonal) hematologic disorder, involving hematopoietic stem cells and characterized by the presence of primitive or atypical myeloid or lymphoid cells in the bone marrow and the blood. "Compared to wild-type PML NBs, the PML A216V variant from arsenic-resistant leukemia patients significantly impairs LLPS." (PMID 39551864, 2024). "Recent publications indicated a strong association between the HBV core protein SUMOylation and the association with promyelocytic leukemia nuclear bodies (PML-NBs) on relaxed circular DNA to cccDNA conversion." (PMID 38567974, 2024). "In contrast, the leukemia-associated fusion protein PML-RARα induces the degradation of HIPK2 by inhibiting PML stabilization of HIPK2, underscoring a novel mechanism in the regulation of leukemogenesis." (PMID 37345014, 2023). "Cells displaying ALT present distinctive features including C-circles made of telomeric DNA, long and heterogenous telomeric tracts, and telomeric DNA co-localized with promyelocytic leukemia (PML) bodies forming so-called ALT-associated PML bodies (APBs)." (PMID 36759506, 2023). "Similar to leukemias driven by PML mutations, H3.3-mutated glioma cells are sensitive to drugs that target PML bodies." (PMID 38066546, 2023). "Herein, we identified promyelocytic leukemia (PML) as a novel miR-762 target gene associated with the ability of this miRNA to regulate endothelial cell and keratinocyte migration." (PMID 35729564, 2022). "It was found to target the leukemia-causing fusion oncogene PML-RAR and promote myeloid cancer cell differentiation." (PMID 35493504, 2022). "To examine the molecular signature governing leukaemia maintenance driven by LncSIK1 loss, we asked the role of LncSIK1 in PML‐RARa catabolism." (PMID 35092119, 2022). "This pattern of expression in mammalian cells is due to the extensive SUMO modification of Promyelocytic leukaemia nuclear bodies (PML-NBs), a process required for PML-NB formation and associated protein-protein interactions." (PMID 33351855, 2020). "This is in contrast to other leukemia-associated rearrangements, such as PML-RARA or BCR-ABL1, that are pharmacologically actionable." (PMID 32115572, 2020). "Detection of ALT-associated promyelocytic leukemia (PML) nuclear bodies (APB) at the telomeres is a technique combining anti-PML immunofluorescence and telomere FISH." (PMID 31706351, 2019). "Recent outcomes have revealed that abnormal increased cytoplasmic localization of PML appears in NPM1-mutated leukemia cells." (PMID 31777586, 2019). "Considering that aberrant cytoplasmic localization of PML was mediated by NPM1-mA in NPM1-mutated leukemia cells 27, we next investigated the effects of NPM1-mA on VCAN-V1 expression." (PMID 31777586, 2019). "We confirmed these results by co-immunofluorescence of hTERT associated with promyelocytic leukemia (PML)." (PMID 30384446, 2018). "The “single” pattern was exclusively associated with the promyelocytic leukemia nuclear bodies (PML-NBs), forming structures known as viral DNA-containing PML-NBs or vDCP-NBs." (PMID 27618691, 2016). "Although RD3 has been shown to be associated with the leukemia gene product PML, the crucial role of RD3 in cancer biology has been overlooked." (PMID 26375249, 2015). "For instance, overexpression of retinoic acid receptor alpha (RARα) due to its fusion to PML (RARα/PML) and estrogen receptor alpha (ERα) expression cause onset of leukemia and breast cancer progression, respectively." (PMID 26244663, 2015). "In ESCs, H3.3, DAXX and ATRX can localize to the promyelocytic leukemia nuclear bodies (PML-NBs) and form ALT-associated PML-NBs (APBs), one of the hallmarks of ALT cells." (PMID 24563217, 2014). "In this study, we analyzed the nuclear localization of ATBF1, and found that ectopically expressed ATBF1 formed nuclear body (NB)-like dots in the nucleus, some of which indeed physically associated with promyelocytic leukemia (PML) NBs." (PMID 24651376, 2014).